SYT2 (synaptotagmin 2)
Description:
Exhibits calcium-dependent phospholipid and inositol polyphosphate binding properties (By similarity). May have a regulatory role in the membrane interactions during trafficking of synaptic vesicles at the active zone of the synapse (By similarity). Plays a role in dendrite formation by melanocytes.
Synonyms: SytII; CMS7; CMS7A; CMS7B; MYSPC
Tractability: Antibody: its Gene Ontology location is reachable by antibodies, with high confidence; UniProt predicts a signal peptide or a membrane-spanning region. PROTAC: ubiquitination databases record sites on it.
Gene: Protein-coding gene on chromosome 1 (202,590,596 to 202,710,526, reverse strand). Ensembl gene ENSG00000143858.
Subcellular location: Cytoplasmic vesicle, secretory vesicle, synaptic vesicle membrane; Cytoplasmic vesicle, secretory vesicle, chromaffin granule membrane; Cytoplasm
Pathways (Reactome):
Vesicle-mediated transport: Cargo recognition for clathrin-mediated endocytosis; Clathrin-mediated endocytosis
Disease: Toxicity of botulinum toxin type B (botB)
Neuronal System: Neurexins and neuroligins
Gene Ontology:
Molecular function: protein binding; calcium ion sensor activity; calcium-dependent phospholipid binding; inositol 1,3,4,5 tetrakisphosphate binding; SNARE binding
Biological process: positive regulation of dendrite extension; calcium-dependent activation of synaptic vesicle fusion; regulation of calcium ion-dependent exocytosis; regulation of synaptic vesicle exocytosis; vesicle-mediated transport
Cellular component: axon; clathrin-coated endocytic vesicle membrane; cytoplasm; dense core granule; exocytic vesicle; plasma membrane; synaptic vesicle membrane; chromaffin granule membrane; membrane
Genetic constraint (gnomAD): Loss-of-function variants: 14 observed, 37.4 expected, observed/expected ratio (o/e) 0.37, 90% interval 0.25 to 0.58. The upper end of that interval is the gene's LOEUF score, 0.58, which puts it in group 2 of 6, group 1 being the genes least tolerant of losing a copy. Missense variants: 350 observed, 508.36 expected, observed/expected ratio (o/e) 0.69, 90% interval 0.63 to 0.75. Synonymous variants: 160 observed, 197.16 expected, observed/expected ratio (o/e) 0.81, 90% interval 0.71 to 0.93.
Gene-disease validity (ClinGen):
ClinGen rates the evidence that SYT2 causes each of these diseases.
congenital myasthenic syndrome 7 (autosomal dominant): Moderate.
Homologues: Orthologues: chimpanzee SYT2 (100% identical), macaque SYT2 (99% identical), rat Syt2 (98% identical), guinea pig SYT2 (98% identical), mouse Syt2 (98% identical), dog SYT2 (96% identical), pig SYT2 (95% identical), tropical clawed frog syt2 (84% identical), zebrafish syt2a (73% identical), rabbit SYT2 (68% identical), zebrafish SYT2 (43% identical). Paralogues in human: SYT1 (77% identical), SYT5 (55% identical), SYT6 (37% identical), SYT10 (37% identical), SYT3 (37% identical), SYT9 (36% identical), SYT7 (36% identical), SYT8 (36% identical), SYT4 (32% identical), SYT11 (31% identical), SYT17 (31% identical), DOC2B (28% identical), and 19 more.
Diseases named in the same sentence as SYT2 in open-access papers:
SYT2 is named in the same sentence as 35 diseases in open-access papers, as found by Europe PMC text mining. Sharing a sentence is not in itself a finding about the gene and the disease. The quoted sentences say what the papers report.
Ataxia (4 papers, 2016 to 2022). Ataxia refers to impaired coordination of voluntary muscle movement. "A similar dramatic reduction and slowdown of evoked release was present in a mouse strain bearing a destabilizing Syt2 mutation and exhibiting ataxia, one of the manifestations of PRRT2 mutations in patients." (PMID 27052163, 2016). "However, Atr-PCΔ mice show ataxia due to a defect of intrinsic neuronal activity mediated by modulating presynaptic firing through interacting between ATR and synaptotagmin 2 (SYT2), rather than cerebellar degeneration." (PMID 35153719, 2021).
congenital myasthenic syndrome (4 papers, 2017 to 2023). Congenital myasthenic syndrome (CMS) is a group of genetic disorders of impaired neuromuscular transmission at the motor endplate characterized by fatigable muscle weakness. "Recessive mutations in SYT2 have also been shown to cause a severe, early onset form of congenital myasthenic syndrome (CMS)." (PMID 36869887, 2023). "However, whole-exome sequencing techniques have now identified point mutations in the human synaptotagmin 2 (syt2) gene in patients with a disease combining congenital myasthenic syndrome and distal motor weakness, suggesting a role for synaptotagmin in neuromuscular disease." (PMID 28953919, 2017). "Studies have shown that SYT2 is one of the disease genes responsible for congenital myasthenic syndromes." (PMID 35730015, 2022). "Synaptotagmin 2, the Ca2+ sensor for fast, synchronized neurotransmitter release at the human neuromuscular junction, has recently been implicated in a dominantly inherited congenital myasthenic syndrome associated with a non-progressive motor neuropathy." (PMID 28953919, 2017).
neuroblastoma (3 papers, 2017 to 2023). Neuroblastoma (NB) is the most common solid, extracranial childhood tumor. "Neuroblastoma cells (N2a) were transfected with tomato-tagged SYT2 and PROT and immunoprecipitation (IP) was performed." (PMID 34210973, 2021). "If needed, sensitivity could be improved further by stably transfecting into the NanoLuc-VAMP2 SiMa neuroblastoma cells the mouse synaptotagmin 2 which has 10 times higher affinity to BoNT/B compared to human synaptotagmin." (PMID 29170639, 2017).
schizophrenia (3 papers, 2017 to 2026). A major psychotic disorder characterized by abnormalities in the perception or expression of reality. "Specifically, we found higher levels of the presynaptic marker for Parvalbumin interneurons synaptotagmin II (Syt2), mirroring observations made in the brain of schizophrenia patients." (PMID 42185248, 2026). "SYT2, downregulated by FASD, is essential for survival and is downregulated in the cortex of autism spectrum disorder (ASD) and schizophrenia patients." (PMID 35268026, 2022).
Lambert-Eaton myasthenic syndrome (2 papers, 2017 to 2023). Lambert-Eaton myasthenic syndrome (LEMS) is an autoimmune, presynaptic disorder of neuromuscular transmission characterized by fluctuating muscle weakness and autonomic dysfunction frequently associated with small-cell lung cancer (SCLC). "A mutation in the homologous residue (P308L) in human Syt2 has been found to cause an autosomal-dominant form of Lambert-Eaton Myasthenic Syndrome in a multigenerational UK family." (PMID 28895532, 2017). "SYT2-CMS, SNAP25-CMS, VAMP1-CMS, UNC13A-CMS, RPH3A-CMS, and LAMA5-CMS are characterized by defects in the SNARE complex, and phenotypically similar to Lambert-Eaton myasthenic syndrome (LEMS)." (PMID 36835142, 2023).
ovarian carcinoma (2 papers, 2021 to 2023). A malignant neoplasm originating from the surface ovarian epithelium. "Amid the nodes involved in our network, SYT2 has been suggested to play a regulatory role in synaptic vesicle trafficking and in promoting metastasis in ovarian cancer." (PMID 37444135, 2023).
Alzheimer disease (1 paper, 2021). A progressive, neurodegenerative disease characterized by loss of function and death of nerve cells in several areas of the brain leading to loss of cognitive function such as memory and language. "In a recent study, synaptotagmin 2 was significantly reduced in postmortem brain tissue of Alzheimer’s disease patients and reliably discriminated Alzheimer’s disease from Parkinson’s disease dementia." (PMID 33578866, 2021).
autism (1 paper, 2024). Persistent deficits in social interaction and communication and interaction as well as a markedly restricted repertoire of activity and interest as well as repetitive patterns of behavior. "There was a nominally significant set-level association with autism (P = 0.03) that would not remain significant if corrected for multiple testing over all language-related and psychiatric traits, with five genes individually associated at P < 0.05: BMPER, GATB, KCNH5, SNCA, and SYT2." (PMID 39133845, 2024).
cognitive decline (1 paper, 2020). "They found a significant loss of SYT2, which implicates that it could be a synaptic marker of cognitive decline in neurodegenerative diseases." (PMID 33280468, 2020).
COVID-19 (1 paper, 2021). A disease caused by infection with severe acute respiratory syndrome coronavirus 2. "ULBP2, SYT2, VMAC, and FOXJ1 followed the same pattern of expression in COPD compared to COVID-19, however, to a much lower level." (PMID 33679887, 2021).
dependence (1 paper, 2017). "In addition, injections of the DNMTs inhibitor RG108 into the mPFC prevented escalation of alcohol consumption, dependence-induced downregulation synaptotagmin 2 (Syt2) gene expression and hypermethylation on CpG#5 of its first exon." (PMID 28614398, 2017).
distal motor neuropathy (1 paper, 2024). "Finally, synaptotagmin 2 (SYT2) on BTA16 is the major isoform that is expressed at the neuromuscular junction with dominant missense variants having been reported as a rare cause of distal motor neuropathy and myasthenic syndrome." (PMID 39766766, 2024).
epilepsy (1 paper, 2021). A brain disorder characterized by episodes of abnormally increased neuronal discharge resulting in transient episodes of sensory or motor neurological dysfunction, or psychic dysfunction. "Its deletion relieves the repression of SYT2 and PROT in promoting membrane fusion to facilitate fast neurotransmitter release, therein rendering ATR-FB∆ mice more susceptible to epilepsy." (PMID 34210973, 2021).
glaucoma (1 paper, 2023). Increased pressure in the eyeball due to obstruction of the outflow of aqueous humor. "We identified multiple genes of interest with higher relative expression in glaucoma-related cell types; examples include NEFM, SYT2 expression in RGCs, AQP5 and KRT3 expression in corneal epithelial cells and CDH6 in ciliary muscle." (PMID 36833422, 2023).
Hip dysplasia (1 paper, 2019). The presence of developmental dysplasia of the hip. "Hyperlaxity of joints and hip dysplasia may occur in SYT2-related CMS." (PMID 30808424, 2019).
male infertility (1 paper, 2021). The inability of the male to effect fertilization of an ovum after a specified period of unprotected intercourse. "However, these KI mice that express the modified Syt2 showed a dominant partial male infertility, suggesting that replacing the entire luminal domain may still disrupt Syt2 function/stability." (PMID 34662366, 2021).
polyneuropathy (1 paper, 2019). A disease or disorder affecting more than one nerve. "Mutations in CMS genes, such as in SYT2, not only manifest in the skeletal muscle but also in the peripheral nerves as polyneuropathy." (PMID 30808424, 2019).
Tremor (1 paper, 2021). An unintentional, oscillating to-and-fro muscle movement about a joint axis. "A recent study showed that the deletion of synaptotagmin-2 (Syt2) from excitatory parvalbumin positive neurons in cerebellar nuclei produced asynchronous transmitter release and action tremor in mice." (PMID 33804860, 2021).
cancer (1 paper, 2022). A tumor composed of atypical neoplastic, often pleomorphic cells that invade other tissues. "The role of SYT2, SCN4A, GPR37, and F2 in cancers has not been well studied." (PMID 36110953, 2022).
infection (1 paper, 2023). The state of being infected such as from the introduction of a foreign agent such as serum, vaccine, antigenic substance or organism. "Therefore, we hypothesize that attachment of the RBD to the HI loop of the AdV fiber could result in preferential infection of Syt2-expressing cells in the brain." (PMID 37819378, 2023).
SYT2 also shares sentences with these, for which no sentence is quoted: alcohol addiction (1 paper); alcoholism (1); attention deficit-hyperactivity disorder (1); autism spectrum disorder (1); cerebellar degeneration (1); cocaine dependence (1); hyperglycaemia (1); mammary tumours (1); mitochondrial DNA depletion syndrome 9 (1); neurodegenerative disease (1); neurodevelopmental disorder (1); neurological disease (1); neuromuscular disease (1); neuropathy (1); periodontitis (1).